CAB39L (calcium binding protein 39 like)
Description:
Component of a complex that binds and activates STK11/LKB1. In the complex, required to stabilize the interaction between CAB39/MO25 (CAB39/MO25alpha or CAB39L/MO25beta) and STK11/LKB1 (By similarity).
Synonyms: bA103J18.3; FLJ12577; MO2L; MLAA-34; MO25-BETA
Tractability: PROTAC: its protein half-life has been measured.
Gene: Protein-coding gene on chromosome 13 (49,308,629 to 49,444,342, reverse strand). Ensembl gene ENSG00000102547.
Subcellular location (Human Protein Atlas): Vesicles
Pathways (Reactome):
Signal Transduction: Energy dependent regulation of mTOR by LKB1-AMPK
Gene Ontology:
Molecular function: protein binding; protein serine/threonine kinase activator activity
Biological process: intracellular signal transduction
Cellular component: cytosol
Genetic constraint (gnomAD): Loss-of-function variants: 15 observed, 25.64 expected, observed/expected ratio (o/e) 0.59, 90% interval 0.39 to 0.9. The upper end of that interval is the gene's LOEUF score, 0.9, which puts it in group 3 of 6, group 1 being the genes least tolerant of losing a copy. Missense variants: 257 observed, 285.78 expected, observed/expected ratio (o/e) 0.9, 90% interval 0.81 to 1. Synonymous variants: 92 observed, 103.12 expected, observed/expected ratio (o/e) 0.89, 90% interval 0.75 to 1.06.
Homologues: Orthologues: chimpanzee CAB39L (100% identical), macaque CAB39L (99% identical), mouse Cab39l (99% identical), pig CAB39L (98% identical), rat Cab39l (97% identical), guinea pig CAB39L (96% identical), tropical clawed frog cab39l (88% identical), rabbit CAB39L (84% identical), dog CAB39L (84% identical), zebrafish cab39l (81% identical), Drosophila melanogaster Mo25 (64% identical), Caenorhabditis elegans mop-25.1 (63% identical), and 1 more. Paralogues in human: CAB39 (81% identical).
Diseases named in the same sentence as CAB39L in open-access papers:
CAB39L is named in the same sentence as 18 diseases in open-access papers, as found by Europe PMC text mining. Sharing a sentence is not in itself a finding about the gene and the disease. The quoted sentences say what the papers report.
gastric cancer (4 papers, 2018 to 2023). A primary or metastatic malignant neoplasm involving the stomach. "Moreover, increased expression of the protein tyrosine phosphatase (PTPRA) gene and promoter methylation of the calcium-binding protein 39-like (CAB39L) gene were associated with gastric cancer." (PMID 31892232, 2019). "More and more evidence is emerging to indicate that CAB39L plays an anti-tumor role in many cancers, such as breast cancer and gastric cancer, but the clinical significance and function of CAB39L in KIRC have not been reported." (PMID 37109674, 2023). "In breast cancer and gastric carcinoma, silencing CAB39L facilitated G1/S phase transition and reduced cell apoptosis and thus promoted tumor progression, while overexpression of CAB39L exerted opposite effects." (PMID 37109674, 2023). "Interestingly, the results also revealed that the mRNA level of CAB39L was downregulated in most cancers, including breast cancer, gastric cancer, and bladder cancer." (PMID 37109674, 2023). "Considering that CAB39L is commonly silenced in gastric cancer patients, metformin may serve as a potential adjuvant therapy for GC treatment." (PMID 30054562, 2018).
acute monocytic leukemia (3 papers, 2017 to 2020). Acute monoblastic leukemia (AML-M5), is one of the most common subtypes of acute myeloid leukemia (AML) that is either comprised of more than 80% of monoblasts (AML-M5a) or 30-80% monoblasts with (pro)monocytic differentiation (AML-M5b). "Our laboratory previously used the SEREX method in U937 cells and identified a novel leukemia-associated gene MLAA-34, a novel splice variant of CAB39L associated with acute monocytic leukemia, that exhibited anti-apoptotic activities in U937 cells." (PMID 29059232, 2017). "Using this approach, we identified a novel leukemia-associated gene, MLAA-34, which is a novel splice variant of CAB39L that is associated with acute monocytic leukemia." (PMID 29059232, 2017).
endometriosis (3 papers, 2015 to 2025). The growth of functional endometrial tissue in anatomic sites outside the uterine body. "The Stage B endometriosis risk allele C of rs11619804 (OR = 1.17(1.07–1.28); P = 4.88 ×10−4), located in CAB39L (Calcium-Binding Protein39-Like), was associated with increased WHRadjBMI (β =0.022, P = 1.06 × 10−5)." (PMID 25296917, 2015). "In addition to 7p15.2, weidentify four more variants with statistically significant evidence of involvement inboth endometriosis and WHRadjBMI (in/near KIFAP3,CAB39L, WNT4, GRB14); two ofthese, KIFAP3 and CAB39L, are novel associationsfor both traits." (PMID 25296917, 2015).
breast carcinoma (2 papers, 2017 to 2023). "On a similar note, Kaplan–Meier analysis showed that breast cancer patients with higher expression of both SESN1 and CAB39L exhibited better survival." (PMID 28698800, 2017). "Altogether these findings indicate that downregulation of miR-21-5p expression by metformin, followed by release of CAB39L and SESN1, contributed to attenuating the mTOR aberrant activity and rendering breast cancer cells more prone to cell death induced by a clinically relevant mTOR inhibitor." (PMID 28698800, 2017).
colorectal cancer (1 paper, 2010). A primary or metastatic malignant neoplasm that affects the colon or rectum. "Ten of these genes (WDR67, RFXAP, RP11-50D16.3, CAB39L, THSD1, SPRY2, TGDS, CLDN10, SLC10A2, CD33L3) have been reported changed in tumor tissues, while only 2 (RP11-50D16.3, SLC10A2) have been reported to appear changed in colorectal cancer." (PMID 20467480, 2010).
escherichia coli infection (1 paper, 2024). Infection with the organism Escherichia Coli. "These two DEPs (LOC109953912 and cab39l) were enriched in the Parkinson’s disease, ubiquitin-mediated proteolysis, gap junction, and phagosome pathogenic Escherichia coli infection pathways." (PMID 38773374, 2024).
metastatic cancer (1 paper, 2023). A carcinoma which has spread from the original site of growth to another anatomic site. "It was discovered that transcriptional levels of CAB39L were much lower in tissues of KIRC patients with advanced and metastatic cancer stages." (PMID 37109674, 2023).
non-alcoholic fatty liver disease (1 paper, 2018). "In addition, top three pathways enriched in CAB39L overexpressing AGS cells, including oxidative phosphorylation, non-alcoholic fatty liver disease and ribosome, were all associated with mitochondrial biogenesis." (PMID 30054562, 2018).
tumor (12 papers, 2010 to 2023). "The results revealed that CAB39L expression was closely associated with tumor stage and histologic grade." (PMID 37109674, 2023). "As expected, stable knockdown of CAB39L promoted cell proliferation in MKN74 cells (P < 0.0001), whereas metformin treatment suppressed the growth of MKN74-shCAB39L cells to a greater extent as compared to MKN74-shNC cells, thereby abrogating the tumor promoting effect of CAB39L loss (P < 0.0001)." (PMID 30054562, 2018). "Although overwhelming evidence suggests that CAB39L is a novel tumor biomarker, there is little research on the transcriptional analysis of CAB39L in KIRC." (PMID 37109674, 2023). "CAB39L expression was markedly lower in tumor samples than normal kidney tissues, especially in kidney renal papillary cell carcinoma (KIRP), KIRC, and kidney chromophobe (KICH)." (PMID 37109674, 2023). "Functional studies suggested that CAB39L functions as a tumor suppressor, as overexpression of CAB39L elicited suppression of multiple cancer phenotypes both in GC cells and an orthotopic mouse model; whilst its knockdown promoted tumorigenesis." (PMID 30054562, 2018). "We revealed that CAB39L possesses tumor suppressive effects in GC cells, that CAB39L mediates its effect by eliciting an anti-Warburg effect via a LKB1-AMPK-PGC1α axis and that promoter methylation of CAB39L predicts poor outcomes in GC patients." (PMID 30054562, 2018). "In this study, we reported the identification of Calcium Binding Protein 39-Like (CAB39L) as a novel regulator of tumor metabolism in GC." (PMID 30054562, 2018). "In keeping with in vitro results, BGC823 xenografts with ectopic CAB39L expression demonstrated a significant reduction in both tumor size and weight (Fig. 3e1–2), with western blot confirming the ectopic expression of CAB39L (Fig. 3e3)." (PMID 30054562, 2018). "Collectively, these data suggest CAB39L exerts a tumor suppressive effect on GC by inducing apoptosis and cell cycle arrest." (PMID 30054562, 2018). "Our data demonstrate that CAB39L is a novel tumor suppressor which suppresses tumorigenesis by promoting LKB1-AMPK-PGC1α axis, thereby preventing a metabolic shift that drives carcinogenesis." (PMID 30054562, 2018). "In summary, we identified CAB39L as a novel tumor suppressor that is frequently silenced by promoter hypermethylation in GC." (PMID 30054562, 2018). "Whether CAB39L regulates tumor growth by influencing the cell cycle in KIRC needs further experimental verification." (PMID 37109674, 2023). "Taken together, it can be assumed that CAB39L may shift aerobic glycolysis to oxidative phosphorylation through the AMPK signal pathway to limit tumor growth." (PMID 37109674, 2023). "The level of CAB39L gene methylation increased with the progression of tumor grade and stage." (PMID 37109674, 2023). "CAB39L is a tumor metabolism regulator with the functions of tumor suppressor." (PMID 34568022, 2021). "The frequent silencing of CAB39L in GC prompted us to hypothesize that CAB39L may function as a tumor suppressor." (PMID 30054562, 2018). "Using in vitro and in vivo models of GC, we demonstrated the tumor suppressive function of CAB39L." (PMID 30054562, 2018). "The tumor suppressive effect of CAB39L is therefore dependent on downstream LKB1-AMPK pathway." (PMID 30054562, 2018). "Besides, rescue experiment by re-expression of CAB39L in MKN74- shCAB39L cells restored the tumor-suppressive effect of CAB39L." (PMID 30054562, 2018). "Moreover, knockdown of LKB1 reversed growth inhibitory effect of CAB39L, indicating that tumor suppression by CAB39L depended on LKB1-AMPK." (PMID 30054562, 2018). "Based on our in vitro results, we next tested the effect of CAB39L on tumor growth in vivo." (PMID 30054562, 2018). "Taken together, CAB39L may play a potential suppressive role in tumor development." (PMID 37109674, 2023). "The frequent silencing of CAB39L in GC suggests that it might function as a tumor suppressor in GC." (PMID 30054562, 2018).
tumor (continued). "Immunohistochemistry (IHC) results from HPA demonstrated that DLGAP5 protein was found to be strongly expressed in BC tumor tissues, while SLC16A6, CAB39L, and HBA demonstrated lower protein expression in BC tissues." (PMID 37142271, 2023). "We previously identified tumor suppressor genes such as SCNN1B and CAB39L 8, 9 that are silenced by promoter DNA methylation in GC patients." (PMID 31534549, 2019). "For instance, miR-21 directly targets tumor suppressive PTEN, SESN1, CAB39L, and RASA1 in different types of cancer to regulate different cancer cell behaviors." (PMID 31500623, 2019). "Knockdown of LKB1 largely abolished growth inhibitory effect of CAB39L in MTT and colony formation assays, suggesting that tumor suppressive function of CAB39L is dependent on LKB1." (PMID 30054562, 2018). "Hence, the down-regulation of CAB39L in GC may contribute to tumor development and progression." (PMID 30054562, 2018). "CAB39, a paralog of CAB39L, has been reported to interact with LKB1 and STE20-Related Kinase Adaptor (STRAD), leading to activation of LKB1, a bona fide tumor suppressor and an upstream kinase that phosphorylates AMPK." (PMID 30054562, 2018). "Moreover, CAB39L is downregulated in both the protein and mRNA level of KIRC and plays an indispensable role in restraining tumor progression." (PMID 37109674, 2023). "Concomitantly, CAB39L silencing using two independent siRNAs in MKN74 cells increased cell viability (P < 0.01) and colony formation (P < 0.05), consistent with the function of CAB39L as a tumor suppressor." (PMID 30054562, 2018). "Given that CAB39L strongly activated LKB1-AMPK pathway in GC, we next sought to determine whether the tumor suppressive effect of CAB39L is dependent on LKB1 and AMPK activation." (PMID 30054562, 2018).
cancer (7 papers, 2018 to 2023). A tumor composed of atypical neoplastic, often pleomorphic cells that invade other tissues. "Second, the prognostic and diagnostic value of CAB39L was only investigated and validated in cancer databases, requiring more clinical research support." (PMID 37109674, 2023). "Background and Objectives: Calcium-binding protein 39-like (CAB39L) has been reported to be downregulated and possessed diagnostic and prognostic values in several types of cancer." (PMID 37109674, 2023). "The mRNA levels of CAB39L were determined in 33 types of cancer from independent databases." (PMID 37109674, 2023). "We found that most of the mTOR pathway-related genes had a high expression level in most cancers, except for a few genes such as CAB39L and PRKAA2, which had a lower expression in most cancers compared to normal tissues." (PMID 34194607, 2021). "HHIPL2, XPO1, SALRNA1, ZBTB45, ANP32AP1, ACTR3BP5, LOC100129138, GPR45, and CAB39L gene deletions were associated with non-cancer subjects without FCH (p < 0.05), while RAB9BP1, LOC101928523, and MALRD1 gene deletions were related to non-cancer patients with FCH (p < 0.05)." (PMID 33431054, 2021).
CAB39L also shares sentences with these, for which no sentence is quoted: leukemia (3 papers); bladder cancer (1); Insulin resistance (1); monocytic leukemia (1); Obesity (1); oral cancer (1); Parkinson disease (1); prostate carcinoma (1).